AFP (alpha fetoprotein)
Diseases named in the same sentence as AFP in open-access papers (continued):
Sharing a sentence is not in itself a finding about the gene and the disease.
tumor (continued). "In this study, patients with low CXI seemed to have larger tumors, more tumor numbers, portal vein invasion, and higher serum AFP and PIVKA-II levels than in those with high CXI, which could describe their poor prognosis." (PMID 35538112, 2022). "In contrast, the response to downstaging as a predictive factor was also confirmed in AFP-negative tumors, as a tumor burden outside the MC at LT is a major risk factor for HCC recurrence (HR 10, 0.0; 3.7–33.3; p < 0.001)." (PMID 35529597, 2022). "Higher rate of tumor metastasis in the liver after surgery may result in poor outcomes of AFP-positive GC." (PMID 35847953, 2022). "Improved the examination of tumor markers are as follows: AFP 86.57ng/ml and HCG 11439 mIU/ml." (PMID 35710558, 2022). "The elevation of AFP levels of >500 ng/ml is associated with the tumor bulk; 80% of small HCCs show no elevation of AFP concentration." (PMID 35547447, 2022). "Moreover, intravenous injection of AFP CAR-T cells suppressed tumor growth rapidly and profoundly in tumor-bearing mice." (PMID 36093115, 2022). "AFP has been reported as a surrogate marker of tumor differentiation and vascular invasion." (PMID 35053580, 2022). "A nomogram was constructed to predict the survival probability at 1-, 3-, and 5-year by integrating RAE1 expression level and clinicopathological characteristics (N stage, gender (male or female), age, prothrombin time (PT), AFP level, tumor status, and pathologic stage)." (PMID 35751040, 2022). "AFP decline during anti-neoplasm treatment has a proven prognostic value in adults." (PMID 35204369, 2022). "Multivariate Cox regression analysis of clinical prognostic information demonstrated that downregulated ABCC6 was not only an independent prognostic marker, but also correlated with some malignant and aggressive clinicopathological features, such as high AFP values and large tumor size." (PMID 35280774, 2022). "AFP is a well-known factor reflecting HCC tumor malignancy; thus, u-HCC patients with high AFP levels may have more aggressive tumors, which are associated with shorter OS." (PMID 35884434, 2022). "Alpha-fetoprotein (AFP) has been established as an accurate tumor marker for the presence of HCC in people when detected at elevated levels, and may be used as an adjunct for monitoring recurrence." (PMID 36136704, 2022). "In conclusion, early AFP response may be a useful predictor of better tumor response and longer PFS and OS in patients with uHCC receiving lenvatinib." (PMID 35251977, 2022). "Additionally, we found that female patients and patients with high AST and AFP, poor tumor differentiation, advanced TNM stage, incomplete tumor encapsulation appeared to exhibit high SHC4 expression." (PMID 35033067, 2022). "All the patients in our study had low AFP, which may suggest favorable biology and impact tumor response." (PMID 36289623, 2022). "This also indicated that AFP fragment could synergize with sorafenib to block the important pathways that involve in tumour growth, proliferation and metastasis, result in inhibit angiogenesis, and promote apoptosis in HCC." (PMID 36181321, 2022). "In the training cohort, maximum tumor diameter, tumor margin, arterial peritumoral enhancement, tumor number, hemoglobin, total bilirubin, direct bilirubin, and AFP were predictive clinical and imaging variables for the presence of MVI in HCC patients (p < 0.05)." (PMID 36577952, 2022). "AFP and its receptor-binding fragments may provide a favorable drug distribution and high accumulation in tumor tissue, which makes their application attractive as vector molecules." (PMID 35328540, 2022). "Univariate Cox regression analysis identified the following factors that affected PFS: tumour lesion number < 3 (OR 0.428, 95% CI, 0.187–0.982; P = 0.045), AFP level < 400 ng/mL (OR 0.448, 95% CI, 0.227–0.883; P = 0.020), and TBIL (OR 1.036, 95% CI, 1.006–1.066; P = 0.018)." (PMID 35836207, 2022).
tumor (continued). "Previous studies have shown that tumor size, vascular invasion, AFP level, and number of lesions may affect the prognosis of patients with HCC, which is consistent with the results of this study." (PMID 36451200, 2022). "However, there were few differences in other tumor markers such as AFP, CA 125, and CA242 between XGC group and GBC group." (PMID 34837350, 2022). "However, another tumor marker PIGR was surprisingly found to be elevated in serum-derived exosomes with the diagnostic AUC of 0.837, higher than that of alpha-fetoprotein." (PMID 35757760, 2022). "Testing of AFP as a tumor marker in peripheral blood, ultrasonography, and contrast-enhanced CT or magnetic resonance imaging (MRI) of the abdomen were completed in follow-up visits which were performed every 2 months during the first 6 month and every half year thereafter." (PMID 35898866, 2022). "This study developed and validated a preoperative prediction model for MVI combining laboratory examinations and contrast-enhanced CT imaging features, which includes maximum tumor diameter (> 50 mm), tumor margin, direct bilirubin (> 2.7 μmol/L), and AFP (> 360.7 ng/mL)." (PMID 36577952, 2022). "Moreover, serum fCK18 levels were significantly correlated with several blood tumor markers, namely AFP (r = 0.279; P < 0.0001) and DCP (r = 0.232; P < 0.001), although the correlation coefficient is low." (PMID 36081568, 2022). "BHCG and alpha-fetoprotein are secreted by the tumor and are used as biomarkers." (PMID 36553112, 2022). "Serum AFP level is not only a significant prognostic predictor for HCC, but is also associated with many metastatic characteristics of HCC, such as MVI, an incomplete tumor capsule, and satellite lesions." (PMID 35715787, 2022). "The value of AFP was positively correlated with tumor diameter (r = 0.3234, P = 0.005)." (PMID 35197961, 2022). "We then combined the inflammatory score with AFP and tumor size to build an MVI prediction model." (PMID 35310437, 2022). "The tumor phenotype obtained from LPC pIL17 -engrafted cells was associated with a greater expression of the CK19 biliary/progenitor cell marker, and an increased number of CD133+ and AFP+ cells." (PMID 35342340, 2022). "Meanwhile, we combined a few selected clinicopathological characteristics, such as BMI, AFP, tumor status, stage, etc., to establish a predictive nomogram model to evaluate the 1-year, 3-year, and 5-year prognosis of HCC patients to achieve accurate prediction of survival." (PMID 35397536, 2022). "The tumor necrosis caused by TACE increased the release of tumor-associated antigens, which has been proven to recruit DCs, increase AFP-specific CD4+T-cell response, synergize with ICIs to increase cytotoxic T lymphocytes, and decrease tumor-infiltrating Treg cells." (PMID 35530353, 2022). "In some patients, miRNA-based tests may be even more sensitive than the classical serum tumor markers—β-hCG, AFP and LDH—which are currently used in the clinic." (PMID 35204369, 2022). "Consequently, metastatic tumor mediators (ki-67, N-cadherin, AFP, and gene expression of cyclin D, TERT, VEGF, and MMP9) as well as functional parameters of metastatic seeds (CSCs) were dramatically downregulated in LC-DF(II) NPs." (PMID 36686682, 2022). "In addition, larger tumor size (P = 0.094), AFP > 200 ng/mL (P = 0.024), and tumor rupture (P = 0.017) were also correlated with significant muscle loss." (PMID 36464698, 2022). "In addition, tumor diameter, AFP level and dose of regorafenib and best response to regorafenib are all related to OS and progression-free survival (PFS) of patients." (PMID 36358825, 2022). "Patients with the larger tumor size had a higher AFP level, had more tumor multifocality." (PMID 35411218, 2022).
tumor (continued). "Univariate Cox regression analysis showed that disease stage, relapse, maximum tumor diameter, and alpha-fetoprotein returning to normal within 2 months postoperatively were risk factors for survival (HRs of 25.43, 26.43, 1.48 and 0.08, respectively, p < 0.05)." (PMID 36601033, 2022). "The tumour distribution was more similar (liver 44% vs. 42%, p = 0.86; lung 54% vs. 49%, p = 0.57, bone 18% vs. 15%, p = 0.69), apart from more distant lymph node metastases in the high AFP group (15% vs. 4%, p < 0.001)." (PMID 35956006, 2022). "One other study performed in HIV-negative patients showed that AFP≥ 400 ng/mL is a reliable tool in the prognosis of HCC patients: HCC patients with a AFP concentration ≥400 ng/mL tend to have greater tumour size, massive or diffuse types, portal vein thrombosis, and a lower median survival rate." (PMID 35186078, 2022). "Notably, patients with low ARHGAP24 in early tumor stage (BCLC: 0 + A; P < 0.01) or low alpha-fetoprotein subgroups (≤ 400 ng/mL; P < 0.05) also had higher probabilities of tumor progression when compared to the patients with high ARHGAP24." (PMID 36168627, 2022). "Besides the presence of MetS, tumor size, AFP, ALBI, and CCI were well-established prognostic factors of HBV-related HCC." (PMID 35356224, 2022). "The results may suggest that tumor biological characteristics of AFP level plays more important role than morphological variables in tumor recurrence and prognosis." (PMID 36203429, 2022). "Our results showed that elevated GLR has a positive correlation with the recurrence of HCC patients with staging I–II after adjustment of age, sex, smoking, operation time, lymphovascular invasion, allogeneic blood, HB, AST, ALP, HBsAg, tumor number, tumor size, AFP." (PMID 35395799, 2022). "This is consistent with a study conducted in malignant disease who found that Cbx4 expression was elevated in HCC tissues, and Cbx4 overexpression was associated to tumor size, pathologic differentiation, and TNM (tumor, node, metastasis) phases as well as the blood level of alpha-fetoprotein (AFP)." (PMID 36672564, 2022). "As generally seen in other treatments, a decline in post-treatment tumor marker level is associated with better efficacy of immunotherapy in advanced HCC; the AFP response at 6 weeks after atezolizumab plus bevacizumab initiation especially seemed to be a potential surrogate biomarker for prognosis." (PMID 35804984, 2022). "Moreover, enhanced LMNB1 expression was found to be closely correlated with advanced TNM stage, poorer histological differentiation, higher levels of AFP, tumor recurrence and tumor metastasis." (PMID 35436411, 2022). "Chi-square test and Fisher exact test illustrated a significant correlation of CEP192 expression levels with pathologic stage (p = 0.008), tumor status (p < 0.001), sex (p = 0.008), age (p = 0.034), AFP expression (p = 0.038), DFS event (p < 0.001), and PFS event (p = 0.007) of HCC patients." (PMID 36238304, 2022). "Additionally, these authors reported a positive correlation between PTTG1 protein concentration and serum alpha-fetoprotein (AFP), portal vein tumor thrombosis, tumor stage, and FGF levels." (PMID 35805898, 2022). "In addition, the sensitivity of AFP reduction was increased from 25% to 52% while tumor size was >3 cm and <3 cm." (PMID 35547447, 2022). "Importantly, tumor eradication was achieved in orthotopic HCC mice when antigenic AFP peptide was replaced with the full-length AFP (A) to form DEXP&A&N." (PMID 35488312, 2022). "The AFP level in our patients probably reflected tumour biology more than disease volume." (PMID 35956006, 2022). "Overall, patients with a higher De Ritis ratio level had lower BMI and albumin levels, but a higher proportion of ALBI grade; had HBV DNA content ≥103 copies/ml, AFP level ≥400 ng/ml, and main tumor size ≥5 cm; and presented with BCLC stage B and C, and tumor thrombus." (PMID 35664791, 2022).
tumor (continued). "However, it has been shown that AFP ≥ 158 ng/mL (AUC = 0.752) is an independent risk factor for MVI, suggesting that high levels of AFP can also respond to tumor cell invasion." (PMID 36577952, 2022). "The univariate analyses revealed that RFS was significantly associated with a final outcome of R grade C–D (p < 0.001), Child–Pugh grade B disease (p = 0.009), an AFP concentration of >100 ng/mL (p = 0.034), tumor size (p = 0.025) and the number of tumors (p = 0.032)." (PMID 33803926, 2021). "In 24–48 h, the tumor SNR of MPDA@SPIO/SA-PEI/AFP-Fth was maintained at 25.3–28.3." (PMID 34819084, 2021). "Predictors of TGR included elevated AFP, low albumin, and smaller tumor size." (PMID 34966854, 2021). "Tumor markers such as AFP and PIVKA-II were also similar in the two groups." (PMID 34855786, 2021). "However, the specificity of AFP as a tumor marker is expected to improve after SVR because AFP production from non-cancer sources is reduced with improvement in inflammation." (PMID 34231046, 2021). "Univariate and multivariate Cox regression analyses conducted on HCC patients with type I and II PVTT after R0 LR demonstrated that type of PVTT (P=0.001), INR level (P<0.001), AFP (P<0.001), tumor diameter (P=0.011), and direct bilirubin (P<0.001) to be independent predictors of OS." (PMID 34395264, 2021). "Importantly, the plasma levels of hsa_circ_0003998 were significantly correlated with higher serum AFP level, larger tumor diameter, microvascular invasion (MVI), and lower differentiation level." (PMID 33477833, 2021). "IHC was performed in 99 tumor specimens to explore the AFP expression in APA-GI patients." (PMID 33996549, 2021). "Considering that genetic changes often occur earlier than clinical/pathological changes, the combination of serum AFP and tumor-related gene expression may enhance the efficacy of screening and early diagnosis of HCC." (PMID 34660300, 2021). "High expression of ELF3-AS1 in patients with HCC was related to T stage (P < 0.001), gender (P = 0.006), residual tumor (P = 0.008), histologic grade (P < 0.001), adjacent hepatic tissue inflammation (P = 0.011), AFP (P < 0.001), and vascular invasion (P = 0.028)." (PMID 34336727, 2021). "All patients had normalised tumour markers (AFP, β-HCG, LDH) prior to R-RPLND." (PMID 34021196, 2021). "The high expression of CTSA mRNA was related to the vascular invasion (P = 0.001), tumor TNM stage (P = 0.004), serum alpha-fetoprotein (AFP) level (P = 0.001), neoplasm histology grades (P = 0.038), and adjacent hepatic inflammation in (P = 0.009) HCC patients." (PMID 34272452, 2021). "Univariate analysis revealed that albumin, total bilirubin, ALBI grade, alpha-fetoprotein (AFP), greatest tumor size, macroscopic vascular invasion, extrahepatic metastasis, BCLC stage, GPS score, mGPS score, Hs-mGPS, NLR score, PLR score, PNI score, SII score, and LCR score were associated with OS." (PMID 33589570, 2021). "The other adjustment variables (age, Child Pugh, tumor size and AFP) did not exhibit strong association with survival." (PMID 33961627, 2021). "Clinical management of TGCTs is extensively guided by imaging technologies e.g. computed tomography or magnetic resonance imaging and by serum levels of tumour markers alpha fetoprotein (AFP), beta Human chorionic gonadotropin (bHCG) and lactate dehydrogenase (LDH)." (PMID 33200255, 2021). "AFP as a dynamic factor can also provide valuable information on the biology of the tumor." (PMID 34638365, 2021). "Finally, in the RETREAT score AFP, vascular invasion and sum of the largest viable tumor diameter (cm) and number of viable tumors on explanted liver were combined to obtain a scoring risk from 0 to >5." (PMID 34638365, 2021). "It shows CAF cells (red) enwrapping a spheroid of tumor cells (green), positive for AFP." (PMID 34947582, 2021). "AFP has also been reported to promote tumor escape from immune surveillance." (PMID 33765973, 2021).
tumor (continued). "In addition to tumor parameters (size and number of nodules), biomarkers, such as alpha-fetoprotein (AFP) and protein induced by vitamin K absence (PIVKA-II), and histopathologic characteristics were included." (PMID 34203396, 2021). "Notably, high PNO1 expression was marginally significantly related with tumor size (p = 0.042), serum alpha-fetoprotein (AFP) level (p = 0.006), and positive rate of Ki-67 (p = 0.013)." (PMID 34050137, 2021). "In particular, it was suggested that the significant activation of VEGF signalling displayed by AFP-high tumours could provide the rationale for the efficacy of ramucirumab in this subpopulation of HCC patients." (PMID 33531690, 2021). "Secondly, given that the variables recorded in the SEER database are stereotyped, some valuable clinical predictors were not involved in this study, including common tumor markers such as AFP, CE-199, molecular susceptibility, and the Fürhman classification." (PMID 34900681, 2021). "Interestingly, we found a strong association between SOX2 expression and the concentrations of serum ALT, a specific enzyme of the liver, and also of the AFP tumor marker." (PMID 34436030, 2021). "Current predictors of HCC recurrence after LT have been limited to tumor burden on the explant, presence of vascular invasion, and elevated AFP, together comprising scores such as the RETREAT score, used to determine the frequency of surveillance for post-LT recurrence." (PMID 34794390, 2021). "Another criterion for the selection of reliable diagnostic HCC tumor markers is the frequency of positive tumor marker detection in patients with AFP-negative HCC." (PMID 34513063, 2021). "Elevated expression of CMTM6 was frequently accompanied with worse malignant phenomenon, such as with high AFP level, large tumor size, advanced TNM stage, vascular invasion in a large cohort of 619 HCC cases (In Zhu’s study, only 75 HCC samples were collected)." (PMID 32770259, 2021). "Anecdotally, PLUNC-positive tumor cells cannot be stained by AFP." (PMID 33912455, 2021). "The results suggested that MPDA@SPIO/SA-PEI/AFP-Fth had a superior ability to enhance the MR contrast of T2-weighted images of tumor region than the other preparations, which was due to its HCC-targeted ability and the combined T2 contrast effect of endogenous ferritin and exogenous SPIO." (PMID 33731140, 2021). "Recently, more and more evidence has shown that intracellular AFP could inhibit the apoptosis of tumor cells." (PMID 34680245, 2021). "From their multivariate Cox’s regression analysis, tumor size, tumor number, AFP level, vascular invasion, Child–Pugh score, objective response after TACE, and NLR were selected as predictors of OS and incorporated into a 14-point risk prediction model (SNAVCORN)." (PMID 34204125, 2021). "In addition, the levels of tumor markers, alpha-fetoprotein, and carcinoembryonic antigen were normal, and amebiasis serology was negative." (PMID 33847652, 2021). "Likewise, low SIRT3 expression was associated with serum AFP levels, which has both diagnostic and prognostic value in the context of HCC, tumor multiplicity and high relapse rate, thus representing a prognostic marker of overall survival in HCC patients." (PMID 33920670, 2021). "Moreover, on analyses of RFS, miR-203 (P=0.017), AFP level (P=0.000), tumor encapsulation (P=0.049) and tumor size (P=0.022) emerged as significant independent prognostic factors." (PMID 34234851, 2021). "For OS, the univariate analysis showed that narrow tumor margin, MVI, the advanced TNM stage, highly recurrent AFP levels, and early recurrence showed association with shorter OS (all P < 0.05), and multivariate Cox regression analysis identified MVI as the only independent risk factor of OS." (PMID 34127007, 2021).